DSG3 (desmoglein 3)
Diseases named in the same sentence as DSG3 in open-access papers (continued):
Sharing a sentence is not in itself a finding about the gene and the disease.
pemphigus (continued). "The results demonstrated that anti-Dsg1 and anti-Dsg3, exhibited superior performance in differentiating between healthy individuals and pemphigus, with AUC values of 0.96 (95%CI: 0.93~1) for anti-Dsg1 and 0.91 (95%CI:0.86~0.96) for anti-Dsg3." (PMID 40661962, 2025). "The levels of anti-Dsg1 and anti-Dsg3 were significantly higher in pemphigus patients, whereas the levels of anti-BP180 and anti-BP230 were significantly elevated in BP patients compared to both disease control patients and healthy volunteers." (PMID 40661962, 2025). "Several studies have shown that most pemphigus-specific auto-ab specifically bind to the N-terminal EC1 domain of Dsg3 that also functions as the major mediator of homo- and heterophilic interactions." (PMID 39450179, 2024). "The mechanism of pemphigus lies in the immune response targeting desmoglein 3 (DSG3) and, to a lesser extent, desmoglein 1 (DSG1)." (PMID 39727486, 2024). "While pemphigus antigens Dsg1 and Dsg3 are functionally glycosylation independent, the glycosylation profile of PV IgG is drastically altered." (PMID 39450179, 2024). "The conventionally recognized antigenic targets in the pemphigus group of diseases are desmoglein 3 (Dsg3) and desmoglein 1 (Dsg1), members of the calcium dependent cadherin superfamily of transmembrane cell adhesion molecules." (PMID 39759530, 2024). "Pemphigus is caused by autoantibody production against desmoglein 1 and 3 (anti‐DSG1 and DSG3), which are involved in the cell‐to‐cell adhesion of keratinocytes." (PMID 39460496, 2024). "Desmoglein 3 autoantibodies are expressed in the mucosal dominant phenotype of pemphigus (pemphigus vulgaris) and desmoglein 1 autoantibodies are present in cutaneous pemphigus." (PMID 38256427, 2024). "Mechanisms of pemphigus relapse include both incomplete B‐cell depletion and the persistence of DSG3‐self‐reactive B‐cell populations that are notably present in patients who relapse but not in those experiencing clinical remission." (PMID 39460496, 2024). "We calculated the levels of DSG-1 and DSG-3 exclusively for the pemphigus patient group, consisting of 10 individuals." (PMID 38399557, 2024). "The two most common subtypes of pemphigus include pemphigus vulgaris (PV), which primarily targets desmoglein 3 with mucosal involvement, as well as pemphigus foliaceous (PF), which primarily targets desmoglein 1, generally without mucosal involvement." (PMID 39355721, 2024). "The hallmark feature of pemphigus is the immune system’s predominant attack on desmoglein (DSG) proteins, primarily DSG-3, DSG-1, or both DSG-3/DSG-1." (PMID 38399557, 2024). "Here we exploited HDAC3- and KLF5-dependent regulation of DSG3 transcription, which was identified by our screens, to rescue DSG3 protein levels and membrane localization in pemphigus models." (PMID 39271654, 2024). "An autoreactive B cell response mainly directed to Dsg 1 and Dsg3 is sustained by a T cell response that is also crucial for pemphigus onset." (PMID 38213911, 2023). "In animal models, an important immunological tolerance against Dsg3 can be found in developing an active disease model for pemphigus." (PMID 36539957, 2023). "Another modification of the pemphigus mouse model involved the transfer of naїve splenocytes from Dsg3-/- mice into Rag2-/- Dsg3+/+ recipients." (PMID 37180099, 2023). "We used AK23, a DSG3-specific autoantibody derived from a pemphigus mouse model as well as IgGs from a patient suffering from PV." (PMID 37450050, 2023). "The predominant subclass of anti‐Dsg3 IgG was IgG4 in pemphigus, suggesting T cell‐dependent isotype switching." (PMID 36539957, 2023). "Pemphigus is a kind of bullous autoimmune disorder in which the autoimmune system targets its own desmosomes (mostly Dsg-1 and Dsg-3) of the mucocutaneous membranes by autoantibodies, resulting in loss of connectivity between keratinocytes." (PMID 38125430, 2023).
pemphigus (continued). "Overall, the depletion of DSG1 and DSG3 in pemphigus activates multiple signaling pathways, which contribute to the pathogenesis of this autoimmune disease." (PMID 37237515, 2023). "ELISAs are typically performed using commercial kits to assess the most commonly occurring autoantibodies seen in AIBD, i.e., DSG1 & DSG3 antibodies in pemphigus, BP180 & BP230 antibodies in pemphigoid diseases and collagen VII antibodies in EBA." (PMID 38074463, 2023). "In pemphigus, it is a reasonable assumption that HLAs that bind with specific Dsg3 peptides are involved in pathogenesis." (PMID 36539957, 2023). "The pemphigus antigens Dsg1 and Dsg3 were downregulated and the keratin cytoskeleton was severely compromised." (PMID 36624106, 2023). "Recent progress in molecular biology has revealed that IgG autoantibodies of classical pemphigus react with Dsg1 or Dsg3." (PMID 36578135, 2023). "Regarding the pemphigus antigen Dsg3, the tolerance mechanisms against Dsg3‐specific T cells in the thymus and periphery are becoming better understood and are described in detail below." (PMID 36539957, 2023). "Dsg3‐reactive T cell clones that induced anti‐Dsg3 antibody production and pemphigus phenotype were originally established from Dsg3−/− mice, where the immunological tolerance mechanism against Dsg3 did not function." (PMID 36539957, 2023). "The most common forms of pemphigus are those characterized by the presence of autoantibodies against the cadherin DSG3 (affecting mainly the mucosae), the cadherin DSG1 (affecting mainly the epidermis), or both simultaneously (mucocutaneous)." (PMID 37237515, 2023). "Mucocutaneous Pemphigus is determined by the presence of autoantibodies targeting both DSG3 and DSG1 and lesions in both sites." (PMID 37237515, 2023). "In vitro culture of lymphocytes isolated from pemphigus skin lesions resulted in anti‐Dsg3 antibody production, significantly decreased by Trm depletion or IL‐21 blockade in the culture system." (PMID 36539957, 2023). "In the so far largest multicenter prospective study, anti-Dsg1/ Dsg3 serum antibodies were, however, detected in 329 (98.5%) of 333 pemphigus sera diagnosed by the clinical picture and direct IF microscopy using widely available assays." (PMID 35755063, 2022). "This study shows that while anti-DSG3 IgG4 were detected in more than 90% of pemphigus sera at baseline, this IgG4 subclass was also present in sera from all but one patient in sustained CR who still had positive circulating anti-DSG3 Abs." (PMID 35371083, 2022). "We focused on co-localization of the pemphigus autoantigens Dsg1 and Dsg3 with plaque proteins Pg and Dp." (PMID 35711465, 2022). "The majority of signalling molecules involved in pemphigus pathogenesis analysed so far including p38MAPK, PLC, and PKC were associated with both Dsg1 and Dsg3." (PMID 34434944, 2021). "Although it seems likely that both Dsg3-reactive Th1 and Th2 cell are important for pemphigus development, most studies have focused on the role of Th2 cells and shown them be critical for the development of the disease." (PMID 35187073, 2021). "Autoantibodies in pemphigus vegetans are against Dsg1 and Dsg3, as well as other proteins constituting the desmosome." (PMID 35187073, 2021). "This was shown first for Dsg3, which was found to form a complex with activated p38MAPK, a process enhanced by pemphigus autoantibodies." (PMID 34434944, 2021). "This cell-surface Dsg3 internalization and depletion was blocked by p38MAPK inhibition in pemphigus mouse models." (PMID 34447768, 2021). "We used desmoglein 3 (Dsg3), a pemphigus antigen expressed in keratinocytes, to analyze peripheral tolerance under physiological antigen-expression conditions." (PMID 34848535, 2021).
pemphigus (continued). "For example, in pemphigus, anti-Dsg1 and anti-Dsg3 antibodies bind to keratinocyte adhesion proteins desmoglein-1 and -3, respectively." (PMID 34068035, 2021). "This is followed by DSG3 internalization that is facilitated by p38 MAPK activation, resulting in the DSG3 exhaustion from the desmosomes, a specific event in PV, leading to pemphigus acantholysis." (PMID 34206820, 2021). "Patients with pemphigus possess Dsg3-reactive Th1 and Th2 cells, with some studies finding comparable frequencies of the two subsets, and others detecting greater numbers of autoreactive Th1 compared to Th2 cells." (PMID 35187073, 2021). "A recent study demonstrated that high numbers of LCs are present in perilesional skin from patients with pemphigus; while in vitro work showed that LCs were able to capture the epidermal antigen Dsg3 via langerin and to present this antigen to T cells." (PMID 35187073, 2021). "Interface dermatitis is the pathological changes that are observed in paraneoplastic pemphigus, one of the subtypes of pemphigus with anti-Dsg3 autoimmunity as well as lupus erythematosus, lichen planus, and graft versus host disease." (PMID 34848535, 2021). "Cloning of the gene coding for the major pemphigus antigens, Dsg1 and Dsg3, has enabled the production of recombinant proteins, which are used to detect IgG autoantibodies by ELISA." (PMID 32642305, 2020). "According to our current knowledge, pemphigus autoantibodies directly inhibit Dsg3 interactions and induce dysregulation of several signaling pathways." (PMID 33193387, 2020). "In 2008, Nishifuji and colleagues reported on the development of an enzyme-linked immunosorbent assay (ELISA) for the detection of circulating IgG AA against DSG3 in dogs with pemphigus." (PMID 33228633, 2020). "We designed an immunosorbent based on an agarose matrix, Affi-Gel 15, and human recombinant desmoglein 3, as a ligand, for a selective removal of autoantibodies from pemphigus patients' sera." (PMID 32742728, 2020). "Of the 141 compounds, 20 prevented pemphigus IgG‐induced Dsg3 internalization from either one or both pemphigus patient IgG preparations by the predefined cut‐off at a concentration of either 0.1 or 10 μM." (PMID 32815159, 2020). "Depending on the subtype, pemphigus antibodies are mostly directed against desmoglein 3 (Dsg3) and desmoglein 1 (Dsg1)." (PMID 31749790, 2019). "On the contrary, the other pemphigus models (DSC3/DSG3 and DSG3) appear to be only partially responsive to m-PSL." (PMID 31275323, 2019). "PV is a complex autoimmune disease with Dsg3 being a central player in pemphigus acantholysis that likely is triggered by a collection of signaling pathways, including Src, p38 MAPK, EGFR, c-Myc, and Rho GTPases, downstream of PV-IgG targeting Dsg3 disruption." (PMID 31582719, 2019). "It was shown that Src can be activated by PV-IgG containing antibodies against Dsg3 as well as by AK23, which constitutes a Dsg3-specific monoclonal autoantibody from a pemphigus mouse model." (PMID 31024527, 2019). "We employed a passive murine pemphigus model that can be induced by intravenous injection of antimurine Dsg3 antibodies (Abs) to mice." (PMID 31570755, 2019). "Our group demonstrated the presence of IgE targeting Dsg3 in patients with pemphigus, which further supports the critical role of Th2 cells in orchestrating the inflammatory response and autoantibody production in pemphigus." (PMID 31293582, 2019). "Herein, using a murine model of pemphigus by targeting Dsg3, we examined how extravasation of blood-circulating IgG is regulated under homeostatic conditions." (PMID 31570755, 2019).
pemphigus (continued). "Altogether, the two pemphigus models reacting against DSG3 have a higher PV score, as compared to the DSC3 mice." (PMID 31275323, 2019). "Taken together, we show that Src contributes to loss of cell adhesion primarily downstream of antibodies against Dsg3 in pemphigus by mechanisms which are both cortactin-dependent and –independent." (PMID 31024527, 2019). "Mice were intravenously injected with sera obtained from two pemphigus patients, who are positive for anti-Dsg3 Abs composed of IgG1 and IgG4 subclasses." (PMID 31570755, 2019). "In the present study, we present two novel animal models of pemphigus developed by a protocol originally established for DSG3 PV." (PMID 31275323, 2019). "Pemphigus is an autoimmune blistering disease targeting the desmosomal proteins desmoglein (Dsg) 1 and Dsg3." (PMID 31057535, 2019). "In response to binding of pemphigus autoantibodies to the keratinocyte surface, Dsg3-mediated homophilic interaction is impaired and desmosomal proteins are depleted from the membrane leading to keratin retraction and Dsg internalization." (PMID 31057535, 2019). "As expected, the vast majority of cultures resulted specific for Dsg1 and/or Dsg3, further confirming the major role of these antigens in pemphigus pathogenesis." (PMID 31275324, 2019). "In contrast to Dsg1, pemphigus autoantibodies against Dsg3 directly interfere with Dsg interaction, which alone is not sufficient to cause loss of keratinocyte adhesion." (PMID 31178865, 2019). "Commercial ELISA systems (MBL, Euroimmun) are available for the detection of autoantibodies against Dsg1 and Dsg3 in pemphigus and against envoplakin in paraneoplastic pemphigus." (PMID 31552014, 2019). "This is in line with the observation that pemphigus autoantibody fractions including autoantibodies targeting Dsg3 activate both Src and p38MAPK." (PMID 31024527, 2019). "Dr. Rüdiger Eming (Philipps-Universität Marburg, Marburg, Germany) described strategies to restore immune tolerance to Dsg3 in the CD4+ T cell compartment by applying an HLA-transgenic mouse model of pemphigus." (PMID 30467542, 2018). "In fact, in a large prospective study with more than 330 pemphigus patients, only 4% of all pemphigus sera and 2.7% of PV and PF sera exhibited anti-desmocollin reactivity, while 98% of sera contained anti-Dsg3 and/or anti-Dsg1 IgG." (PMID 30233569, 2018). "Two representative classical IgG types of pemphigus are pemphigus vulgaris (PV) and pemphigus foliaceus (PF), which react with desmoglein 3 (Dsg3) and Dsg1, respectively, although there are many other forms of pemphigus." (PMID 29867971, 2018). "Nevertheless, reduced cell cohesion in response to D4476 was further impaired by additional application of AK23, a monoclonal anti-Dsg3 autoantibody derived from a pemphigus mouse model." (PMID 29922278, 2018). "It is inconsistent with other studies, which demonstrated that decrease in anti-Dsg-1 antibody and anti-Dsg-3 antibody level is parallel with the clinical improvement in pemphigus patients." (PMID 30083474, 2018). "The serological diagnosis of pemphigus relies on the demonstration of circulating anti-Dsg1 and anti-Dsg3 by ELISA and/or by indirect immunofluorescence (IIF) on monkey esophagus substrate." (PMID 29740444, 2018). "A few reports in literature describe the existence of antibodies against Dsg1 and/or Dsg3 in patients affected by skin conditions other than pemphigus especially patients affected by lichen planus." (PMID 29740444, 2018). "By stimulating PBMC from pemphigus patients and controls with Dsg3 protein ex vivo, authors identified autoreactive IL-21-secreting cells in 50% of the pemphigus patients." (PMID 30065726, 2018). "For instance, it was shown that Dsg3 overexpression slows down its internalization and degradation and reduces monolayer fragmentation in response to pemphigus antibodies." (PMID 29922278, 2018).
pemphigus (continued). "There are two major subtypes of pemphigus: pemphigus vulgaris (PV), which is characterized by autoantibodies to Dsg3, and pemphigus foliaceus (PF), characterized by autoantibodies to Dsg1." (PMID 28184292, 2017). "The simpler model proposes that pemphigus pathogenic autoAb inhibit, either sterically or allosterically, the interaction of DSG1 and DSG3 from desmosomes of adjacent keratinocytes (trans-interaction), inducing loss of cell adhesion." (PMID 28928733, 2017). "In pemphigus vulgaris (PV), the most common clinical variant of pemphigus, several in vitro and in vivo studies demonstrated the critical role of Dsg3-specific CD4+ T cells in the generation of Dsg3-specific auto-ab." (PMID 26872212, 2016). "The very strong correlation of IL-27 with the anti-Dsg3 IgG titers implicates a disease-specific function of IL-27 in the production of auto-ab in pemphigus." (PMID 26872212, 2016). "It is well established that Dsg3 is targeted by pemphigus autoantibodies and plays a crucial role in pemphigus pathogenesis." (PMID 25629808, 2015). "Whilst the production of pathogenic antibodies is key to the development of pemphigus, recent evidence implies that both T cells and B cells with autoreactivity towards Dsg3 are necessary for the pathogenesis of pemphigus disease." (PMID 24900992, 2014). "Since inhibition of RhoA has been shown to be induced by pemphigus autoantibodies that disrupt Dsg3 and Dsg1 adhesion we also performed RhoA pull down in parallel using the GST fused Rhotekin-PBD." (PMID 22796473, 2012). "Inhibition of Rac1 and RhoA by pemphigus autoantibodies targeting Dsg3 and Dsg1 showed disruption of cell–cell adhesion and blister formation in epidermis." (PMID 22796473, 2012). "Internalization of desmoglein-3 in response to pemphigus autoantibody was found to undergo clathrin-independent internalization, early endosomal localization, and subsequent lysosomal degradation." (PMID 22312325, 2012). "The recent availability of cDNA clones for pemphigus antigens has allowed the production of recombinant desmoglein 1 and desmoglein 3 molecules and the development of an ELISA approach in order to determine levels of antibodies to them." (PMID 20049340, 2009). "The recent availability of cDNA clones for pemphigus antigens has allowed the production of recombinant DSG1 and DSG3 molecules and the development of an enzyme-linked immunosorbent assay (ELISA) approach in order to determine levels of antibodies to them." (PMID 20049340, 2009). "Transmembrane desmosomalproteins: desmoglein 1 (Dsg1) and desmoglein 3 (Dsg3) are pemphigus targetantigens." (PMID 18584045, 2008). "It is res iudicata in pemphigus pathologies that Dsg3 is the autoantigen of the vulgaris form, whereas Dsg1 is the autoantigen of the foliaceous form." (PMID 16925820, 2006). "Notably, in the discrimination of pemphigus and BP, for Dsg1, Dsg3, and BP180 antibodies, the AUC values of CLIA were 0.95 (95%CI: 0.92~0.98), 0.84 (95%CI: 0.77~0.91), and 0.87 (95%CI: 0.82~0.93), which were the best among the three methods." (PMID 40661962, 2025). "Pemphigus disease area index (PDAI), IGC, IG%, C-reactive protein, neutrophil/lymphocyte ratios, platelet-to-lymphocyte ratio (PLR), anti-desmoglein 1, and anti-desmoglein 3 levels in patients with pemphigus were recorded retrospectively, and the statistical relationship between them was evaluated." (PMID 40068041, 2025). "In particular, Veillonella, which has been reported to reduce the risk of asthma and bronchiolitis by inducing a mixed Th1/Th2/Th17 lung inflammatory response, was depleted among patients with active pemphigus, thus explaining the observed inverse correlation with anti-Dsg3 antibody titers." (PMID 40649854, 2025). "Concurrently, both anti-Dsg1 and anti-Dsg3 antibody levels, as well as blood methoxyephedrine, decreased, suggesting that rituximab, in combination with other agents, was an effective therapeutic option for treating pemphigus." (PMID 40135007, 2025).